EGFL7 (EGF like domain multiple 7)
Diseases named in the same sentence as EGFL7 in open-access papers (continued):
Sharing a sentence is not in itself a finding about the gene and the disease.
tumor (continued). "Our study showed that Egfl7 expression in HCC promotes tumour progression in a paracrine manner by recruiting and activating LFs into CAFs, which results from elevated FAK and AKT phosphorylation by signal transduction of ανβ3 integrin." (PMID 37480091, 2023). "Although the mechanism is still poorly characterized, possibly the increase in MAPK pathway can upregulate the expression of EGFL7, leading to an increase in (lymph)angiogenesis and tumor aggressiveness." (PMID 37957249, 2023). "miR-126 downregulates epidermal growth factor-like domain multiple 7 (EGFL7), a tumor-suppressor in OSCC, thereby regulating vascular endothelial growth factor (VEGF), Notch, and Wnt signaling pathways." (PMID 37304135, 2023). "Some studies have demonstrated that Egfl7 can promote tumour EMT and that HCC cells with EMT can also express α-SMA." (PMID 37480091, 2023). "EGFL7 has the traits of early onset and rendering a relative small selective advantage during tumor’s evolution to drug resistance, which is similar with those driver genes identified in tumorigenesis have." (PMID 36309484, 2022). "Using experimental approaches, it has been demonstrated that, when expressed by cancer cells, EGFL7 promotes tumor escape from immunity by downregulating the activation of tumor blood vessels." (PMID 35630004, 2022). "Blocking the expression of EGFL7 in tumor neovascularization will help inhibit tumor growth and metastasis and provide a new approach for tumor treatment." (PMID 36072982, 2022). "EGFL7 promotes glioma growth and stimulates tumor vascularization by generating mature blood vessels covered by pericytes and smooth muscle cells." (PMID 36530974, 2022). "Expression of EGFL7 within the tumor microenvironment (epithelium and/or adjacent endothelium) was detected in 13 of 59 (22.03%) HGOSCs." (PMID 35630004, 2022). "The signaling axis formed by EGFL7 and one of its receptors, beta 3 integrin, has emerged as a key mediator in the regulation of tumor metastasis and drug resistance." (PMID 33804387, 2021). "EGFL7, through its multiple binding partners and cellular receptors, can be found on various cell types, including tumor cells and ECs." (PMID 33804387, 2021). "EGFL7 controls intercellular and cell–matrix communication, which are key features of tumor progression and metastasis, by hijacking the receptor tyrosine kinase epidermal growth factor receptor (EGFR), integrin, and Notch signaling pathways." (PMID 33804387, 2021). "All these features from EGFL7 contribute to an unstable vessel wall and promote the vessel leakiness that is characteristic of tumor ECs." (PMID 33804387, 2021). "Endothelial cells release growth factors such as epidermal growth factor-like protein-7 (EGFL7), which contributes to the formation of the tumor vasculature." (PMID 33804387, 2021). "The effects of EGFL7 on tumor cells and ECs and its diversity of binding receptors enable EGFL7 to impinge on tumor survival strategies." (PMID 33804387, 2021). "Since many anti-cancer drugs require tumor cell cycling, keeping tumor cells in a quiescent state is just another trick by which EGFL7 enhances drug resistance." (PMID 33804387, 2021). "Because a lack of adhesion factors prevents lymphocytes from binding to ECs, a necessary step for cells to cross the vasculature and enter the tumor bed, EGFL7-induced alteration of adhesive properties endows tumors with the ability to escape immune attack." (PMID 33804387, 2021). "In GBM, endothelial EGFL7–integrin signaling promotes the formation of new blood vessels and therapeutic EGFL7 blockade synergizes with anti-VEGF to more effectively impair tumor angiogenesis and growth." (PMID 34131655, 2021). "A deeper understanding of the role of EGFL7 in controlling the fate of tumor-initiating cells and cancer cells and the identification of new ECM binding partners or signaling receptors will open up new avenues for cancer treatment." (PMID 33804387, 2021).
tumor (continued). "EGFL7 contributes to the branched and disorganized architecture of tumor endothelium with irregular multi-layered EC lining and an inconsistent smooth muscle and pericyte sheath." (PMID 33804387, 2021). "It was reported that EGFL7 binds to EGFR wildtype but not to the active mutant EGFR variant III, leading to b-catenin activation and upregulation of EGFL7 expression and tumor growth." (PMID 33804387, 2021). "Here, we found that EGFL7 is upregulated in OS, expressed by both tumor cells and vascular endothelial cells, and that chemotherapy deregulated the expression of EGFL7 in vivo and in vitro." (PMID 32117731, 2020). "A significant downregulation of EGFL7 by chemotherapy was confirmed by IHC, qPCR, and WB, in both OS tumor tissues and OS cell lines." (PMID 32117731, 2020). "This revealed that EGFL7 protein levels were significantly higher in OS tumor tissues, predominantly localized in the cytoplasm of both vascular endothelial cells and OS tumor cells, compared to the low levels observed in CS tissues." (PMID 32117731, 2020). "As an endogenous regulator of endothelial cell activation, EGFL7 promotes tumor progression by reducing the expression of endothelial molecules that mediate immune cell infiltration and participate in tumor immune escape mechanisms." (PMID 33391349, 2020). "IF analysis showed that both OS tumor cells and vascular endothelium cells expressed high levels of cytoplasmic EGFL7 protein." (PMID 32117731, 2020). "Our results showed that the EGFL7 expression is upregulated by both OS tumor cells and vascular endothelial cells." (PMID 32117731, 2020). "ICC and IF analyses showed that EGFL7 protein was highly expressed in the cytoplasm of OS cell lines and in OS tissues, indicating that the EGFL7 protein is expressed by OS tumor cells in vivo and in vitro." (PMID 32117731, 2020). "To determine the effect of chemotherapy on EGFL7 expression, we analyzed OS tumor tissues obtained from biopsies before and surgical resection after neo-adjuvant chemotherapy for each patient (matched pairs)." (PMID 32117731, 2020). "The first was that EGFL7 expression by OS tumor cells is upregulated in OS, and this was confirmed using a variety of experimental methods." (PMID 32117731, 2020). "In patient samples, EGFL7 was highly expressed in the cytoplasm of OS tumor cells and vascular endothelium cells." (PMID 32117731, 2020). "Accumulating evidence suggested that EGFL7 plays a crucial role in cancer biology by modulating tumor angiogenesis, metastasis, and invasion." (PMID 32812032, 2020). "Epidermal growth factor-like domain-containing protein 7 (EGFL7), which is up-regulated in several cancers, is involved in neoplasm growth and metastasis." (PMID 30953521, 2019). "We chose EGFL7 as our candidate for next experiments due to the tumor suppressor role of JMY in ccRCC." (PMID 30953521, 2019). "Further, Col IV expression in the basement membrane of tumor blood vessels was significantly reduced after anti‐EGFL7 and anti‐VEGF antibody treatment." (PMID 30065025, 2018). "The vessel‐specific KO of EGFL7 significantly increased the median survival of tumor‐bearing mice (38 days) as compared to 33 days in WT littermates." (PMID 30065025, 2018). "Both models displayed enhanced tumor growth rates as well as reduced survival upon the ectopic expression of EGFL7." (PMID 30065025, 2018). "Epidermal growth factor-like domain 7 (EGFL7) is secreted by the endothelium of blood vessels, and its expression increases with the development of tumor growth and metastasis." (PMID 29363485, 2018). "Morphologically, tumors expressing high levels of EGFL7 displayed an increase in tumor vasculature and an increased maturation state of these vessels." (PMID 30065025, 2018). "Human EGFL7 mRNA, as measured by qRT–PCR, was gone in all three xenografts already at early passages when compared to the primary human tumor." (PMID 30065025, 2018).
tumor (continued). "These comparisons across data furthermore indicate that tumors from patients with the rs9411215 GG genotype presented with a lower EGFL7 tumor expression but this is based on a rather small subsample (N = 40)." (PMID 28539619, 2017). "In contrast, cir-EGFL7 is more likely to reflect the overall state of activated tumor angiogenesis from the entire tumor burden in the patient." (PMID 28539619, 2017). "Patients with the primary tumor in situ presented with significantly higher levels of cir-EGFL7 (approximately 4 fold) than those who had previously undergone tumor resection." (PMID 28539619, 2017). "Our study investigated the relationship between miR-126 and EGFL7, as well as the effects of miR-126 on tumor proliferation and angiogenesis of HCC." (PMID 27611944, 2016). "Our study found that low miR-126 expression was associated with tumor progression via VEGF and EGFL7 activation." (PMID 27611944, 2016). "Epidermal growth factor-like domain 7 (EGFL7) is secreted by normal blood endothelial cells, at sites of pathological angiogenesis, and by tumor cells." (PMID 28066431, 2016). "Nevertheless, tumor weights of transplanted tumors in the miR-126 mimics and si-EGFL7 groups were lower than the blank and miR-126 inhibitors + si-EGFL7 groups (all P < 0.05)." (PMID 27611944, 2016). "Higher levels of EGFL7 have been correlated with poor prognosis in some tumor types such as colorectal cancer." (PMID 28066431, 2016). "This is in accordance with EGFL7 functioning as a pro-angiogenic protein enhancing tumour growth and potentially also dissemination of tumour cells." (PMID 25592646, 2015). "The VA estimates of EGFL7 were significantly higher, and the estimates of miRNA-126 significantly lower, in regional lymph node metastases than in primary tumours." (PMID 25592646, 2015). "The intra-tumoural EGFL7 VA was significantly higher in primary tumours from patients with recurrent disease than in patients without relapse in both stage II and III, p = 0.019 and p = 0.001, respectively." (PMID 25592646, 2015). "The EGFL7 VA was significantly higher and the miRNA-126 VA significantly lower in regional lymph node metastases compared to primary tumours, p = 0.01 and p < 10−6, respectively." (PMID 25592646, 2015). "For statistical power, only the VA estimates of EGFL7 and miRNA-126 in the liver metastases were compared with the corresponding expressions in the regional lymph node metastases and the primary tumours." (PMID 25592646, 2015). "Estimates of EGFL7 VA in primary tumours of stages II and III were significantly higher in the case of relapsing disease and primarily disseminated tumours (stage IV), compared to tumours without relapse." (PMID 25592646, 2015). "More recently, miR-126 down-regulation has been linked to RCC progression, and has been shown to act as a tumor suppressor in various cancer types including RCC through regulating target genes such as CRK, VEGF, and EGFL7 in cancer cells." (PMID 26416448, 2015). "MiR-126, derived from a common precursor structure located within the epidermal growth factor-like domain 7 (EGFL7) gene, is frequently down-regulated in a variety of malignancies and acts as a potential tumor suppressor." (PMID 25551621, 2014). "Egfl7 can promote tumor growth by repressing ICAM-1 and VCAM-1 expression, then limiting immune cell infiltration, as observed in breast and lung carcinoma murine models." (PMID 24734218, 2014). "A recent study proposed EGFL7 increases the metastatic potential of human hepatocellular carcinoma by driving migration and invasion of tumor cells." (PMID 20529320, 2010). "Taking into account the previously discussed data on the involvement of miR-126 in cancer it would be of interest to address the potential interplay of the EGFL7 protein and miR-126 within the tumor vasculature as well as the tumor cells themselves." (PMID 20529320, 2010).
tumor (continued). "Similarly, the extracellular matrix protein EGFL7 (epidermal growth factor-like protein 7), secreted by blood vessels in GB, has been shown to enhance pericyte coverage and stabilize tumor vasculature, reducing vascular permeability." (PMID 39796646, 2024). "Therefore, in this study, we extended the knowledge of Egfl7 in HCC by showing that Egfl7 plays a paracrine role in remodelling the tumour microenvironment by recruiting and activating CAFs." (PMID 37480091, 2023). "There are several studies regarding EGFL7 expression in different tumor types." (PMID 37957249, 2023). "In addition, we further identified EGF-like domain multiple 7 (Egfl7) as a key tumour cell-secreted protein that promotes fibroblasts recruitment and activation." (PMID 37480091, 2023). "ERG inhibition reduced the expression of VE-cadherin and EGFL7 that may result in decreased proliferation and increased apoptosis due to junction instability, hence, inhibit tumor metastasis." (PMID 37310937, 2023). "Strikingly, CAFs activated by paracrine Egfl7 could further remodel the tumour microenvironment by depositing fibrils and collagen and in turn facilitate HCC cell proliferation, invasion and metastasis." (PMID 37480091, 2023). "Egfl7 can also modulate tumour immune microenvironment by mediating immune cell infiltration." (PMID 37480091, 2023). "CAFs activated by Egfl7 through the ανβ3 integrin signaling pathway could further remodel the tumour microenvironment and in turn facilitate HCC cell proliferation, invasion and metastasis." (PMID 37480091, 2023). "However, the EGFL7-status of the tumor microenvironment (cancer epithelium and adjacent endothelium) had no predictive and prognostic value in the analyzed cohort of HGOSC patients." (PMID 35630004, 2022). "This may be somewhat surprising, given that elevated expression of EGFL7 may play a crucial role in cancer biology by modulating tumor angiogenesis." (PMID 35494025, 2022). "However, lncRNA SBF2-AS1 (SBF2 antisense RNA 1), which is upregulated by NFAT5 in glioblastoma cells, can sponge miR-338-3p to release the inhibition of EGFL7 and subsequently stimulate angiogenesis in tumours." (PMID 34064510, 2021). "EGFL7 expression rises again during vascular injury, during pregnancy, in regenerating endothelium following arterial injury, in growth plate injury, in atherosclerotic plaques, and in growing tumors, often mainly in tumor ECs." (PMID 33804387, 2021). "Together, EGFL7 stimulates Flt3/Flt3 ligand signaling in ETPs that resulted in the accumulation of immature ETPs and a paucity of circulating T cells and contributes to impaired antigen-directed cytotoxicity against tumor cells." (PMID 33804387, 2021). "EGFL7 compromises the anti-tumor response on two levels: it impairs the production of terminally differentiated T lymphocytes and it prevents lymphocytes from crossing the vasculature into the tumor bed." (PMID 33804387, 2021). "Interestingly, the amount of EGFL7 expressed by tumor cells was higher than that expressed by ECs in OS." (PMID 32117731, 2020). "EGFL7 mRNA and protein expression was found to increase in OS cell lines and tumor tissues of OS." (PMID 32117731, 2020). "NF-kappa B signaling plays a crucial role in inflammation and immune response, which may be an important signal pathway for EGFL6 and EGFL7 to interfere with tumor immunity and tumor stromal cell infiltration." (PMID 33391349, 2020). "EGFL7 expression in human cancer needs to be carefully evaluated, as EGFL7 may play complex roles in cancer, being potentially secreted by tumor cells, ECs, or both." (PMID 32117731, 2020). "It has been demonstrated that EGFL7 can regulate the collective migration of endothelial cells (ECs) and acts as a chemoattractant for cell migration to promote the angiogenesis of tumors, and tumor escape from immunity by repressing ECs activation." (PMID 32117731, 2020).
tumor (continued). "EGFL7 may promote tumor escape from immunity by downregulating the expression of leukocyte adhesion molecules in endothelial cells, thus repressing immune cell extravasation into tumors." (PMID 32117731, 2020). "For example, VEGF, endothelin-1 (ET-1), and EGFL7 are tumor-secreted proteins that decrease cellular adhesion molecule (CAM) expression by tumor endothelium, which in turn blocks T cell transendothelial migration and subsequent trafficking of T cells into tumors." (PMID 32117236, 2020). "Therefore, as a vital tumor-inducer, EGFL7 involving the epigenetic network in ccRCC progression holds promise for ccRCC-targeted therapy." (PMID 30953521, 2019). "Consistently, we also observed suppression of EGFL7 in these tumor tissues." (PMID 31245291, 2019). "EGFL7 is also a secreted angiogenic factor that can result in pathologic angiogenesis and enhance tumor migration and invasion via the NOTCH signaling pathway, a conserved intercellular signaling pathway that regulates interactions between physically adjacent cells." (PMID 31717838, 2019). "The angiogenic couple has-microRNA-126 (miRNA-126) and epidermal growth factor-like domain 7 (EGFL7) are transcribed from the same gene and regulates all aspects of angiogenesis and may influence the ability of tumor cells to disseminate." (PMID 35582589, 2019). "Furthermore, with the exception of the vascular endothelial cells in solid osteosarcoma tumor, EGFL7 is significantly expressed in tumor cells." (PMID 29363485, 2018). "Both EGFL7 and miR‐126/126* have been linked to the clinical outcome of GBM patients as these molecules have been implicated in the regulation of several tumor types." (PMID 30065025, 2018). "Both results are consistent with the findings of this study, which suggests that the activation of the PI3K-Akt pathway in tumor cells may be the common mechanism in EGFL7 promoting the growth and metastasis of the tumor." (PMID 29363485, 2018). "This study demonstrates that miR-126 might decrease cell proliferation, induce apoptosis, and inhibit tumor angiogenesis in HCC by inhibiting EGFL7 via down-regulating the ERK signaling pathway." (PMID 28881749, 2017). "Importantly, EGFL7, as a type of epidermal growth factor, is highly expressed in the blood vessels of a variety of tumor and tumor adjacent tissues." (PMID 27611944, 2016). "The differences between expressions in primary tumours and regional lymph node metastases were significant regarding both parameters with the EGFL7 demonstrating higher VA in the regional lymph node metastases and the miRNA-126 lower VA, compared to the primary tumours, respectively." (PMID 25592646, 2015). "Finally, EGFL7 is currently being investigated in Phase II clinical trials by Genentech for its role in promoting tumor angiogenesis." (PMID 25705891, 2015). "There have been several reports of EGFL7 expression in various tumors and tumor cell lines." (PMID 20529320, 2010). "Parsatuzumab (MEGF0444A), a humanized monoclonal antibody targeting EGFL7, exhibits immunomodulatory effects and has demonstrated anti-angiogenic activity, tumor growth inhibition, and improved survival in various xenograft and genetically engineered mouse tumor models." (PMID 40427057, 2025). "In addition, EGFL7 overexpression was correlated with tumor size and recurrence, which means that EGFL7 may be considered a potential marker for assessing tumor behavior and the target of future anti-tumoral treatment." (PMID 37958474, 2023). "As majority of previous studies focus on transcriptional regulation of EGFL7/miR-126 by DNA methylation in multiple tumor cell lines, our brand new finding in this article suggested that EGFL7 and miR-126 mRNA levels could be regulated via DNA methylation as well as single nucleotide polymorphisms." (PMID 35494025, 2022). "Their finding indicated EGFL7 could play a role in tumoral angiogenesis and tumor progression." (PMID 35494025, 2022).